CCL2 (C-C motif chemokine ligand 2)
Diseases named in the same sentence as CCL2 in open-access papers (continued):
Sharing a sentence is not in itself a finding about the gene and the disease.
tumor (continued). "GSCs secrete chemokines (such as VEGF, CCL2, CCL5, and CCL7), to recruit GAMs to tumor mass and induce M2 type polarization of GAMs, aiding their transformation and proliferation by building a tumorigenic TME." (PMID 36969167, 2023). "Increased GAM density correlates with tumor grade and a marked increase in GAM chemoattractant CCL2." (PMID 37368789, 2023). "Two inflammatory factors IFNγ and CCL2 were elevated in the liver after YB1 administration, but only IFNγ was found to be responsible for the anti-tumor effect." (PMID 38020179, 2023). "CCL2, also known as monocyte chemoattractant protein 1 (MCP-1), is thought to be an important chemokine for the recruitment of macrophages to the tumour microenvironment." (PMID 38022682, 2023). "In conclusion, these experiments demonstrate that FAM171B promotes CCL2 secretion via HNRNPU, resulting in macrophage infiltration and tumor progression." (PMID 37915048, 2023). "Macrophages are relocated to tumor areas and differentiate into TAMs in response to various cytokines, such as IL-34, CSF1, members of VEGFs, and chemokines, such as CCL5 and CCL2." (PMID 37958467, 2023). "Empty or Ccl2 expressing KPC cells were then transplanted orthotopically into the pancreas of C57BL/6 mice and animals randomized into treatment groups following tumor formation to assess the impact on NK cell immune surveillance in vivo." (PMID 37142692, 2023). "Accordingly, inhibiting transcriptional regulators of CCL2/CCL17, like p38 and AKT, significantly improved tumor sensitivity to sorafenib." (PMID 38139412, 2023). "OV-mediated ICD triggers the release of IL-6, IL-8, IFN-β, IP-10 (CXCL10), MCP-1 (CCL2) and KC (CXCL1) from cancer cells to recruit different immune cells and initiate an anti-tumor response." (PMID 36831636, 2023). "Other studies showed that the chemokines CCL2, 3, 4, and 5 as well as CXCL9 and 10 were involved in T-cell migration into a melanoma tumor microenvironment." (PMID 35795658, 2022). "In fact, tumor stromal mesenchymal stem cells (MSCs) in the TME are also involved in macrophage recruitment, and MSCs highly express various chemokines, especially CCL2, which increase the recruitment of monocytes/macrophages to the TME." (PMID 35740975, 2022). "On the other hand, there are considerable evidence that TAMs induce tumor chemotherapy resistance through the release of inflammatory cytokines and chemokines such as IL-6, CCL18, TNF-α, CCL2, and CXCR4." (PMID 36679900, 2022). "Tumor-derived CCL2, in combination with CCR2 on the surface of monocytes, recruits monocytes to infiltrate the tumor microenvironment or metastatic locations and promotes the TAMs to polarize into M2-TAMs." (PMID 36403055, 2022). "Other studies have reported that IL-8, GM-CSF, TNF-α, YAP1, CXCR2 and CCL2 promote G-MDSC recruitment in CRC and confer tumor immunotherapy resistance to CRC." (PMID 35740594, 2022). "In vivo, significant modulation of cytokine gene expression (particularly CCL2 and CCL5, and C-X-C motif chemokine ligand 10) was observed, with in vitro data indicating that CCL2, CCL5, and CXCL10 were produced by tumor cells after ATR inhibition plus RT." (PMID 36612206, 2022). "Second, the group of cytokines were triggered in response to the resection procedure and then sustained in the newly regrown tumor (IL4, IL5, IL10, IL17, CCL2, IFN-γ and GM-CSF)." (PMID 35884700, 2022). "It is believed that malignant tumor cells can secrete chemokines (CCL2 and CXCL2) to recruit macrophages and MG, which gather around tumor cells, thereby promoting tumor formation and evading immune cell attack." (PMID 35693633, 2022).
tumor (continued). "CAFs are active factors for monocyte recruitment toward tumor cells by stromal-derived growth factor-1 (SDF-1) and CCL2 secretion, promoting their trans-differentiation into the M2 macrophage phenotype." (PMID 35053602, 2022). "Chemokines that recruit monocytes into tumor tissues include CCL family proteins, VEGF, colony stimulating factor (CSF)-1, placental growth factor and monocyte chemotactic protein-1 (MCP-1, also known as CCL2)." (PMID 35493517, 2022). "After anti-HER2 treatment, for the tumor with HER2 amplification, the release of cytokines such as CCL2, CCL21, VEGF, and CXCL1 was downregulated, and the immunosuppressive factors of the tumor microenvironment were improved." (PMID 36211361, 2022). "The chemokines CCL2 and CCL7, which are known as ligands of CCR2, promote the invasion and metastasis of tumor cells and induce immunosuppression." (PMID 35320940, 2022). "At the same time, TAN-N2 presents an anti-inflammatory profile, exhibiting higher levels of CD184 (CXCR4), arginase-1, CCL2, CCL5, VEGF, IL-8, and MMP-9, supporting tumor growth, invasion, and metastasis." (PMID 35741003, 2022). "Mast cells are recruited by the microenvironmental chemokines, such as CCL2, CXCL1, CXCL8/IL8, and CXCL10, to tumor tissues, and are activated by pro-inflammatory cytokines, such as stem cell facto (SCF), IL33, PGE2, leukotriene B4, and osteopontin, in there." (PMID 36211375, 2022). "In OSCC, P. gingivalis infection contributes to the enhanced CXCL8 and CCL2 secretion in the TME, which in turn recruits CD66b+ TANs to the site of neoplastic cells and the promotion of tumor development." (PMID 35784290, 2022). "PMN-MDSC actively communicate with cancer cells through inflammatory mediators and growth factors such as IL8, IL17a, CCL2, TNFα, BV8, VEGFα, and TGFβ plays important roles in various aspects of tumor cell dissemination, invasion, and angiogenesis." (PMID 35504900, 2022). "Tumor cells also release many cytokines including CCL2, CXCL12 and CSF1 that attract TAMs to help tumor escape by producing IL-10 and also directly inhibiting CAR T-cells via PD-1-PD-L1 interaction." (PMID 36569859, 2022). "Many preclinical studies showed high efficacy of CCL2/CCR2 antagonists; for instance, targeting CCR2 with a small-molecule inhibitor not only reduced recruitment of M2-type macrophages but also induced tumor infiltration of activated CD8+ T cells." (PMID 35592338, 2022). "Studies in both humans and mice have shown that these immature monocyte precursors, as well as CD8+ T cells and natural killer (NK) cells are actively recruited into tumors via tumor-derived chemokines (e.g., CCL2/MCP-1, CCL3/MIP-1⍺, and CCL4/MIP-1β)." (PMID 36059473, 2022). "Especially, M2 phenotype can secrete various factors such as CCL2 to weaken the sensitivity of CRC to oxaliplatin and other drugs, which suggest that TAM is expected to become a tumor therapeutic target." (PMID 35186730, 2022). "Conversely, FAT-WT patients had suppressive TME with high expression of CCL2, CXCL12, CXCL14, CD40, ENTPD1, TGFB1, and VEGF; these factors have been confirmed to promote angiogenesis, invasion, and metastasis of tumor cells." (PMID 35836939, 2022). "Another cytokine, CCL2, has been shown to play an important role in the regulation of HCC tumor growth, metastasis, and host immune response." (PMID 35163821, 2022). "CAFs also produce CCL2, CXCL12, IL-6, IL-10, glycoprotein CHI3L1, macrophage colony-stimulating factor to promote the migration of monocytes into tumor tissue and support their transdifferentiation into the M2 phenotype." (PMID 36324128, 2022). "In turn, activated adipocytes secrete chemokines (CCL2, and CCL5), cytokines (IL-1β, IL-6, TNF-α), and angiogenic factors (VEGF), all required for the promotion of tumor growth, angiogenesis and metastasis." (PMID 35493456, 2022).
tumor (continued). "A quantitativestudy on tumor inflammation-related mRNA expression revealed inductionsof key gene expressions, such as STAT1, CXCL10, CCL5, and CCL2, andrejuvenation of TME with enhancement in T cell, macrophage, NK cell,chemokine, and cytokine functions." (PMID 36153998, 2022). "DARC can internalize chemokines (i.e., CCL2, CCL11, CXCL1, CXCL2, CXCL3, CXCL5, CXCL7, CXCL8) that promote angiogenesis or formation of blood vascular, which can foster tumor growth, as well as promote endothelial cell survival via inhibiting apoptosis." (PMID 36497078, 2022). "A recent study found that increased CCL2 induces MCPIP1 expression via the JAK2-STAT3 signaling pathway, which promotes tumor growth." (PMID 35875135, 2022). "In particular, macrophage chemoattractant molecules [e.g., C-C Motif Chemokine Ligand 2 (CCL2)/monocyte chemoattractant protein 1 (MCP-1), colony-stimulating factor 1 (CSF-1)] play a major role to recruit TAMs into the tumor microenvironment." (PMID 35327359, 2022). "Myeloid-derived suppressor cells (MDSCs) are also present in TME in high amounts, contributing to tumor invasion and growth, while they are regulated by many tumor-derived substances, such as CCL5, as well as CCL2." (PMID 35743107, 2022). "For instance, in this study, the concentration of CCL2 was significantly higher in the tumor-bearing mice and in the plasma of E0771-bearing mice; however, OPN was high in concentration in 4T1 plasma and tumor tissue." (PMID 36230508, 2022). "Summary of the involvement of CCL2, CCL17, and CCL22 in different health problems in the cases of pain, immunity, and tumor studies." (PMID 36555280, 2022). "Thus, this discovery is significant in light of observations that tumor-associated macrophages and monocytes are not only more abundant in IBC than in non-IBC specimens, but also provide a source for inflammatory cytokines when exposed to the IBC cell-derived chemokine CCL2." (PMID 35565421, 2022). "Cancer cells produce IL-10, CCL2, and VEGF that induce M2 macrophage polarization, promoting tumor immune evasion." (PMID 36555392, 2022). "Intriguingly, the mesenchymal tumor foci in the three mGBM patients consistently highly expressed two cytokines, i.e., LIF and CCL2." (PMID 34987659, 2022). "The activated STING pathway promoted the production of type I IFN, which induced CCL2, CCL7, and CCL12 expression, mobilizing monocytes to tumours." (PMID 35365161, 2022). "Among them, CCL2 activates the PI3K/Akt/mTOR signaling pathway to promote formation of endocrine resistance feedback loops in the TME, which improves tumor growth." (PMID 35672862, 2022). "First, hypoxia‐triggered release of chemoattractants (i.e., CCL2, CCL5, CXCL12, CSF‐1, and VEGF) from tumor cells and non‐tumor cells to enhance TAMs precursor monocytes recruitment." (PMID 37323705, 2022). "Blockade of CCL2/CCR2 and CXCLs/CXCR2 enhanced the anti-tumor effect of TACE treatment in this model." (PMID 36403057, 2022). "In vitro treatment with trabectedin decreased the production of CCL2, CXCL8, IL-6, VEGF and PTX3 by myxoid liposarcoma (MLS) primary tumor cultures and/or cell lines, and freshly isolated ovarian cancer cells from ascites." (PMID 35299737, 2022). "This modification inhibits the potential of CCL2 to recruit CD8 T cells in the tumor bed and promote tumor growth." (PMID 36429101, 2022). "To further investigate changes in the tumor microenvironment, we determined the levels of TAM‐produced cyto/chemokines Ccl2, Ifnγ, Cxcl10, Cxcl9, Csf1, Csf3, and Il‐6 in the peritoneal lavage." (PMID 36221913, 2022). "There is extensive evidence to indicate that the CCL2/CCR2 and CXCLs/CXCR2 axes can stimulate tumor growth and angiogenesis, and promote the infiltration and activation of host immune cells." (PMID 36403057, 2022). "In turn, neutrophils secrete numerous chemokines, such as CCL2 (MCP-1) and CCL3 (MIP-1), CCL19, and CCL20, to attract monocytes and dendritic cells into the tumor microenvironment." (PMID 36111233, 2022).
tumor (continued). "Macrophages secrete various growth factors such as TGF-β, VEGF, PDGF, cytokines such as M-CSF and interleukins, chemokines such as IL-6, IL-10, CCL2, and CXCL, and enzymes such as MMPs which promote tumor growth." (PMID 36679900, 2022). "Additional studies aimed toward determining specific CCL2-, CCL7-, and CX3CL1-expressing areas and cell types within the tumor would need to be conducted to support these concepts." (PMID 36685592, 2022). "In the TME, VEGF, CCL2, and CD36, among others, facilitate recruitment of monocytes that differentiate into M2 macrophages and stimulate tumor progression and metastasis." (PMID 36555392, 2022). "Tissue-resident and circulating macrophages are recruited to tumor sites via cytokines and chemokines released by tumors, such as M-CSF, GM-CSF, IL-8, CCL20, VEGF, and CCL2." (PMID 35884798, 2022). "Among them, immune-related genes such as CCL2, CCR2, CXCR4, and CCR5 play a role in the recruitment of TAMs in tumor development and progression." (PMID 35874816, 2022). "Immature DCs can be recruited into the TME, attracted by tumor-secreted factors such as CCL2, CCL20/MIP3a, CCL25, CCL5, CXCL12, CXCL1, and CXCL5, while mature DCs reside in areas surrounding the tumor." (PMID 35267487, 2022). "In breast cancer, palmitoylated proteins in tumor EVs can act as TLR2 ligands leading to upregulation of proinflammatory cytokines and chemokines including CCL2, IL-6 and GCSF in macrophages." (PMID 35320943, 2022). "CCR2 has been reported to serve as the primary functional receptor for CCL2 in the TME, and the CCL2/CCR2 axis is known to play a crucial role in tumor progression." (PMID 34874922, 2022). "This study also demonstrated that CRC-induced TAMs promote tumor migration and invasion by its secreted IL6 that inhibits expression of a tumor suppressor miR-506-3p followed by production of CCL2 to further recruit TAMs." (PMID 36211375, 2022). "Another group studying brain metastasis, showed that miR-19a carried from astrocyte exosomes to tumor cells led to reduction of PTEN and increased CCL2 via NFκB in tumor cells driving suppressive myeloid infiltration." (PMID 35320943, 2022). "M2-Mφs suppress tumor immunity and accelerate tumor progression by secreting immune suppressive factors, such as cytokines (TGF-β and IL-10) and chemokines (CCL2, CCL17, CCL22, and CCL24)." (PMID 35155237, 2022). "It has also been reported that neutrophils interact with tumor cells by using the same molecular machinery that induces EMT such as TGF-β, IL-8, CCl2, TNF-α, and IL-17a." (PMID 36091114, 2022). "Further, nitration of CCL2 by MDSC-derived nitric oxide, prevents the infiltration of T cells into the central tumor confining them to the peripheral stroma." (PMID 35504900, 2022). "It was shown that DNMT1-mediated DNA methylation and EZH2-mediated H3K27me3, in the enhancer region, suppressed CCL2 expression in SCLC cells, thereby enhancing tumor progression." (PMID 35770088, 2022). "PYK2 modulates key signaling pathways mediated by CCL2/CCR2, CXCR4, and IL‐4Rα/pSTAT6, and positively regulates macrophage recruitment and polarization, tumor angiogenesis, and tumor growth." (PMID 35092356, 2022). "In particular, inflammatory factors secreted after a surgical intervention such as IL-8, TNF, and CCL2 can promote neutrophil infiltration in addition to SDF1 and plasminogen activator inhibitor 1 secreted by tumor cells." (PMID 35311140, 2022). "Pro-tumor/anti-inflammatory macrophages are reported to secrete excessive angiogenic cytokines such as VEGF, IL-6, IL-8, CCL-2, and MMP-9, which results in aberrant angiogenesis and the hypoxic H&N-specific TME in vitro and in vivo." (PMID 35992863, 2022). "During hyperthermia, cells under heat stress enhance immune response by promoting the release of more exosomes rich in tumor antigens, chemokines (including CCL2, CCL3, CCL4, CCL5 and CCL20, etc.)and HSP to APC to identify and destroy tumor cells." (PMID 36032103, 2022).
tumor (continued). "For example, secretion of CCL2 by cells populating the TME, such as CAFs and tumor cells, leads to the enrichment of Tregs and of MDSCs." (PMID 39301518, 2022). "Studies have indicated that CAFs upregulate the levels of CCL2, CCL26, IL-6 and LOXL2 in HCC, achieving a stronger tumor metastatic phenotype." (PMID 35589690, 2022). "In concert with tumor-derived chemokines (e.g., CXCL1, CCL2, and INFγ), CXC chemokines produced by tissue-resident immune cells promote the accumulation of neutrophils within the TME." (PMID 35504900, 2022). "In general, our study identified KLF15 as a tumor suppressor in TNBC, and illustrated that KLF15 suppresses TNBC proliferation and metastasis by targeting and downregulating CCL2 and CCL7." (PMID 36347994, 2022). "In the TME, CAFs-secreted CCL2, CCL5, CCL17, IL-1, IL-6, IL-13, and IL-26 can also promote a Th2 and Th17 CD4+ polarization, at the expense of anti-tumor Th1 response." (PMID 36338519, 2022). "It is reported that CAFs secrete CCL2, CCL5, CCL7, and CXCL16 chemokines into the tumor microenvironment, promoting the HCC cells invasion and metastasis by activating either hedgehog or TGF-β pathways." (PMID 35589690, 2022). "The expression of CCR2b on GDH-CAR T cells enhanced trafficking to CCL2-secreting neuroblastoma 10-fold, compared to non-CCR2b-expressing CAR T cells, and increased the relative anti-tumour activity." (PMID 35205725, 2022). "This can be explained by an indirect effect of CCL2 on the recruitment of TAMs (and their differentiation into M2) which inhibit the infiltration of CD8 T cells at the tumor site." (PMID 36429101, 2022). "The combined application of siRNA and drugs to block the CCL2/CCR2–STAT3 axis can inhibit the activity of TAMs in the CSC niche, thus enhancing the phagocytic activity of macrophages and inhibiting tumor growth and metastasis." (PMID 35740975, 2022). "This emphasised the key association of D14 neutrophils, PD-L1+ myeloid cells and Ly6Cintermediate monocytes with CT26 tumour size, and a more distant relationship with D7 myeloid cells, CCL17, CXCL1, CCL2, CXCL10 levels, and D14 IL-10 level." (PMID 35226704, 2022). "Compared to fibroblasts from normal tissues, the top upregulated genes in tumor-derived fibroblasts were CXCL8, CXCL2, CCL2, CXCL3 and CXCL1, and the top downregulated genes were IGFBP5, PTGDS, CCN5, CFD, and RAMP1." (PMID 36357663, 2022). "We found that the high-risk group was significantly associated with higher expression level of immune checkpoints and immune inhibitory factors, including CCL2, CTLA4, CXCR4, IL6, LAG3, PDCD1, and TGFB1, indicating tumor immune evasion." (PMID 36092894, 2022). "It has been reported that immunomodulatory proteins and chemokines, including CSF-1, CCL2, FTH, FTL, and TGFβ, are highly enriched in exosomes produced by hypoxic tumor cells." (PMID 36224346, 2022). "Instead, the most significant difference among tumor foci from same patient was microenvironment-related genes (such as LIF and CCL2), emphasizing the critical involvement of these genes in various tumor evolution routes." (PMID 34987659, 2022). "For tumor cell metastasis, the CCR4 antagonist reduced the lymph node metastasis more effectively than the CCL2 neutralizing antibody." (PMID 35177591, 2022). "And IL-33 can stimulate the production of cytokines (IL-4, IL-6) and chemokines (CCL2, CCL3, CCL7, CXCL1), which are also involved in the construction of the tumor microenvironment." (PMID 36110250, 2022). "Signatures specific to the transition into a tumor M-MDSC included the following: downregulation of cell cycle, upregulation of chemotaxis/Ccl2 signaling, and activation of pathways for myeloid and macrophage differentiation." (PMID 36480485, 2022). "The most studied signaling axis in this context has been the CCL2/CCR2, as CCR2 is highly expressed in tumors and have been shown to stimulate macrophages recruitment in the tumor microenvironment." (PMID 35757002, 2022).